IL10 (interleukin 10)
Diseases named in the same sentence as IL10 in open-access papers (continued):
Sharing a sentence is not in itself a finding about the gene and the disease.
Hypertension (continued). "However, the associations of hypertension with lesions of a large number of immune factors including IL-17, MCP-1, IL-6, TGF-β, IL-10 and others have not been fully characterized." (PMID 36195874, 2022). "There are 2 major proinflammatory actions driving hypertensive cardiovascular remodeling and hypertension: leukocyte recruitment into cardiovascular tissues followed by T cell/IL-17–driven inflammation and, simultaneously, a destabilized/reduced antiinflammatory CD4+FoxP3+ Treg/IL-10 response." (PMID 35133978, 2022). "As IL‐10 level is decreased in hypertensive conditions this may be primarily involved in the increased production of TNF‐α in many models of experimental hypertension such as ANG II‐dependent hypertensive rats and Dahl salt‐sensitive rats." (PMID 24744897, 2014). "However, our data shows that T2DM patients with hypertension had significantly lower levels of IL-β and Caspase-1 and slightly higher levels of IL-6 and IL-10, compared to patients with no hypertension." (PMID 23762057, 2013). "Previous work has proven that endogenous IL-10 limits angiotensin II (ANG II)-mediated oxidative stress, inflammation and vascular dysfunction both in vivo and in vitro, suggesting a protective action of IL-10 in vascular diseases such as arterial hypertension." (PMID 20462420, 2010). "The vascular effects of ovine hemoglobin polymerized with glutaraldehyde exposure included the absence of hypertension, minimal endothelial damage with slight alterations in inducible nitric oxide synthase (iNOS), and reduced vascular inflammation mediated by interleukin-10 (IL-10)." (PMID 40431578, 2025). "Moreover, the results highlighted the idea that MVO could regulate the expression levels of targets, especially for TNF, CHRM1, ACE, IL10, PTGS2, REN, and F2, as well as neuroactive ligand–receptor interaction, the calcium signaling pathway, and PI3K-Akt signaling pathway to treat hypertension." (PMID 35308213, 2022). "Indeed, hypertension induces microglial activation in the hypothalamic paraventricular nucleus (PVN) and induces microglial cells participation in the proinflammatory state with the local secretion of IL-1-beta, IL-6, and TNF-alpha and a decrease of anti-inflammatory cytokines, notably IL-10." (PMID 31737062, 2019). "Given the counterregulatory effects of the AT2-R, ACE2, and IL-10 on AT1-R, ACE1, and TNF-α overactivity, these results implicate that increased expression of AT2-R, ACE2, and IL-10 may play a protective role in the development of hypertension in intact females." (PMID 26783414, 2016). "In OSA patients with hypertension, OA did not affect circulating inflammatory marker levels (white blood cells count, CRP, IL-6, IL-10, and TNF-a)." (PMID 35866792, 2022). "Patients with hypertension but without LV hypertrophy showed reduced monocyte surface CD163 expression and plasma IL10 levels, but increased plasma TNF-α." (PMID 34368120, 2021). "DCs lacking CD1d reduce IL-10 production by NKT cells, and the administration of IL-10 to CD1d-KO mice may significantly reverse Ang II-induced hypertension and cardiac remodeling by activating STAT3 and inhibiting the TGF-β1 and NF-kB signaling pathways." (PMID 33612829, 2021).
myocardial infarction (142 papers, 2008 to 2026). Gross necrosis of the myocardium, as a result of interruption of the blood supply to the area, as in coronary thrombosis. "For example, in a myocardial infarction model, IL-10 destabilizes mRNA encoding TNF-α, leading to less harmful left ventricular remodeling and reduced apoptosis of cardiac cells after injury." (PMID 32850791, 2020). "And IL-10-deficient mice revealed increased neutrophil infiltration, infarct size, and myocardial necrosis after acute myocardial infarction." (PMID 24739487, 2014). "In an in-vivo study in rats, it has been observed that the progression of experimentally induced heart failure subsequent to myocardial infarction was associated with a decrease in IL-10/TNF-α ratio." (PMID 21949832, 2011). "IL-6, IL-10, IL-12, KC have been implicated in I/R injury after myocardial infarction." (PMID 23072542, 2012). "In a mouse model of myocardial infarction (MI), administration of m10@T-MNVs enhanced intramyocardial IL-10 mRNA expression and cytokine production." (PMID 41695467, 2026). "One study found that IL-10 reduced myocardial infarction size and improved cardiac function through the PI3K/Akt signaling pathway in MIRI rat." (PMID 40386050, 2025). "Studies have found that mice with myocardial infarction experience a decrease in left ventricular ejection fraction and increased expression of IL-1β, IL-18, and IL-10-mRNA after sleep deprivation." (PMID 40644492, 2025). "Several research studies demonstrate that IL-10 can eventually attenuate apoptosis and facilitate cardiac remodeling after myocardial infarction." (PMID 38397797, 2024). "Studies on DN derived from myocardial infarction in diabetic mice show that treatment with IL-10 led to a reduction in renal collagen-I, attenuating fibrosis." (PMID 39518925, 2024). "During myocardial infarct, the population of B-1a cells in pericardial adipose tissue increases and these cells start to release IL-10, improving the outcome of acute myocardial infarct by reducing inflammation, injury and preserving cardiac function." (PMID 39095816, 2024). "To date, no scientific study has revealed the role of colchicine in postacute myocardial infarction excessive inflammation via IL-10 levels." (PMID 39200761, 2024). "In a mice model of myocardial infarction with IL-10 KO, exosomes derived from endothelial progenitor cells did not exhibit myocardial repair." (PMID 38835975, 2024). "Studies have shown augmented infiltration of iNKT cells in the heart following a myocardial infarction, and further research has demonstrated that αGC-activated iNKT cells mitigate MI/R injury through increased expression of IL-10." (PMID 38879568, 2024). "In contrast, Saccharina japonica (formerly Laminaria japonica) (Phaeophyceae) fucoidan significantly increased the level of IL-10 in serum in rats with a model of myocardial infarction." (PMID 37760952, 2023). "IL-10 lowered the myocardial infarct size and improved cardiac function in diabetic animal subjects, improved capillary density and lowered apoptosis rate and inflammation in the marginal zone of the infarct." (PMID 38137807, 2023). "Parallel to our findings, high sera levels of IL-10 and TNF-alpha were associated with admitted patients with myocarditis and those with acute myocardial infarction." (PMID 36967438, 2023). "Phagocytosis is reported to enhance interleukin-10 (IL-10) expression in macrophages after myocardial infarction, which helps resolve inflammation and promote repair." (PMID 37601043, 2023). "IL-10 has been demonstrated to improve cardiac remodeling after myocardial infarction by stimulating M2 macrophage polarization and fibroblast activation." (PMID 35425785, 2022). "The authors of another study concluded, that IL-10 inhibits inflammation and attenuates left ventricular remodeling after myocardial infarction via activation of STAT3 and suppression of HuR." (PMID 36209229, 2022).
myocardial infarction (continued). "A positive correlation between serum IL-10 levels with LVEF in patients after myocardial infarction suggests the implication of IL-10 in predicting acute and chronic heart failure." (PMID 36297479, 2022). "There was an increase in the titers of IL-4 and IL-10 at D30 after myocardial infarction compared to D1 (P=0.013 and P<0.001, respectively, Wilcoxon test), while IL-6 titers did not change (P=0.31, Wilcoxon test)." (PMID 33495783, 2021). "The administration of these IL-10 gene-edited amniotic MSCs in an acute myocardial infarction mouse model showed higher anti-inflammatory properties and enhanced recovery of heart function, also providing a favorable environment for neovascularization." (PMID 33796536, 2021). "IL-10 improved myocardial infarction; which is hampered in patients with diabetes due to MSC dysfunction." (PMID 35097003, 2021). "In previous studies in mice, inhibition of miR-375 by interleukin-10 administration or anti-miR-375 therapy enhanced cardiac recovery and reduced inflammatory response after myocardial infarction by activation of the PDK-1-AKT pathway." (PMID 34708100, 2021). "Krishnamurthy P, Rajasingh J, Lambers E, Qin G, Losordo DW, Kishore R. IL-10 inhibits inflammation and attenuates left ventricular remodeling after myocardial infarction via activation of STAT3 and suppression of HuR." (PMID 34133599, 2021). "Interleukin-10 promotes heme clearance pathways and is cardioprotective in a murine diabetic myocardial infarction model." (PMID 32879134, 2020). "This is true in different types of tissue, including models of pulmonary fibrosis and myocardial infarction, in which IL-10 influences proteolytic enzymes to lyse the ECM and decrease macrophage TGF-β1 expression to prevent fibrosis." (PMID 32850791, 2020). "IL-10 significantly reduced myocardial infarct size (P < 0.05, vs. vehicle); IL-10 plus SnPP partially reversed the protective effect of IL-10 on infarct size (P > 0.05 vs. vehicle)." (PMID 32879134, 2020). "Recent studies have demonstrated that β-oxidation of AC-derived lipids is necessary for IL-10 production (proresolving cytokine) and subsequent wound healing in a mouse model of myocardial infarction." (PMID 33077427, 2020). "Of particular note, the initial increase in Ccl3/Ccr5 and Il10 that we have noted at AC disease onset has also been observed in myocardial infarction." (PMID 32529556, 2020). "The application of HMGB-1 after myocardial infarction also decreased levels of IL-1, IL-6, IL-10 and vascular endothelial growth factor (VEGF)." (PMID 32403440, 2020). "It is further observed that treatment with IL-10 contributes to protecting the left ventricular function, attenuates cardiac inflammation, inhibits fibrosis, and improves ventricular remodeling in myocardial infarction or pressure overload mouse model." (PMID 33456490, 2020). "Catabolism of apoptotic cell (AC)–derived lipids promotes IL-10 production and subsequent wound healing in a mouse model of myocardial infarction." (PMID 33077427, 2020). "Further experimental studies showed that an inhibition of IL-10/Stat3 in myocardial tissues recruits inflammation cells, damages the function of the heart, and enhances mortality after myocardial infarction (MI) in mice." (PMID 33456490, 2020). "It has been reported that IL-10 treatment produces beneficial effects in controlling adverse cardiac remodeling following pressure overload or acute myocardial infarction in rodents." (PMID 33192505, 2020). "Kishore’s group established a cardioprotective role of IL-10 in mouse models of acute myocardial infarction and pressure-overloaded myocardium." (PMID 30682162, 2019). "IL-10 is well characterized as an anti-inflammatory factor and protective factor in myocardial infarction in diabetic animals." (PMID 31886288, 2019). "In a rat model of myocardial infarction, transplanted MSCs help reduce the inflammatory response and this was, in part, due to increased levels of IL10." (PMID 30803370, 2019).
myocardial infarction (continued). "We showed that the IL-10 levels increased in cardiac tissues, while they decreased in the peripheral serum at 1 week and 2 weeks post myocardial infarction, compared with that in the control group." (PMID 31011288, 2019). "In current study, we also demonstrated that CRISPRa engineered BM-MSCs which overexpressed IL-10 protected against myocardial infarction in diabetic mice too." (PMID 31164920, 2019). "The increase in IL-10 in myocardial infarct patients was found to be correlated with systemic pro-inflammatory activity evaluated with thrombosis, plaque rupture and heart destruction related to IL-6 and TNF-α plasma concentrations." (PMID 29742255, 2018). "For example, mice that received RIPC treatment showed alleviated myocardial infarction, together with elevated cardiac IL-10 expression, following artificially induced ischemia-reperfusion." (PMID 29232398, 2017). "IL-10 is an antiinflammatory cytokine which contributes to improvement in left ventricle functional recovery after myocardial infarction in a cultured cell study." (PMID 24739487, 2014). "In this regard, it has been shown that treatment with IL-10 in a murine model of myocardial infarction inhibits inflammatory parameters and participates in the cardiac remodeling process via activation of STAT3." (PMID 24260222, 2013). "It has been shown that central gene transfer of IL-10 reduces hypothalamic inflammation in heart failure rats after myocardial infarction." (PMID 23691105, 2013). "MSCs have been shown to decrease proinflammatory cytokine gene expression in experimental acute lung injury, myocardial infarction and acute renal failure and to upregulate IL-10 expression in rat models of myocardial infarction and cerebral infarction." (PMID 23971414, 2013). "In keeping with these observations, bone marrow, mononuclear cell-derived IL-10, attenuates T-cell infiltration and cardiac remodeling after myocardial infarction, which prevents cardiac dysfunction." (PMID 22916095, 2012). "Additionally, it has been demonstrated that IL-10 enhances heart function and myocardial wall compliance after myocardial infarction by lowering the collagen I/III ratio." (PMID 39104386, 2024). "When IL-10 is injected into mice with myocardial infarction, fibroblast activation (proliferation, migration and collagen production) could be significantly observed under the influence of macrophage M2." (PMID 37180776, 2023). "However, IL-10 gene deletion enhanced neutrophil infiltration, increased inflammation, enlarged myocardial infarction area, and myocardial necrosis in ischemia-reperfusion mice." (PMID 36911741, 2023). "In addition, açaí pulp supplementation doses of 2% and 5% for 3 months diminishes concentration of interleukin-10 modulating the inflammatory process and decreased the deposit of collagen attenuated cardiac remodeling after myocardial infarction in rats." (PMID 37626388, 2023). "However, IL-10+ regulatory B cells show anti-inflammatory properties and facilitate cardiac remodeling, and IL-10–producing B cells are enriched in murine pericardial adipose tissues and ameliorate the outcome of acute myocardial infarction." (PMID 37629019, 2023). "Moreover, the utilization of 100 mg/kg roselle aqueous extract for 7 days has been proven to alleviate inflammation by attenuating the elevation of plasma troponin-T, IL-6, and IL-10, as well as downregulating IL-10 in rat models of myocardial infarction." (PMID 37375755, 2023). "Interestingly, IL-1, IL-6, CCL2, and CCL3 expression was reduced, whereas Arg1, IL4Rα, and IL-10 expression were increased in macrophages incubated with exosomes derived from the myocardial infarction group." (PMID 35548775, 2022). "IL-10 plays an important role in the final outcome of myocardial infarction." (PMID 36297479, 2022). "Moreover, decreases in the levels of TNF-α and IL-1β, and increases in IL-10, were also shown in a rat model of myocardial infarction." (PMID 35161351, 2022).
myocardial infarction (continued). "A 2 week supplementation with red wine grape pomace reduced premature death, changed TNF-α and IL-10 levels, increased plasma antioxidant activity, and attenuated myocardial infarction and dysfunction, confirming the cardioprotective effect of red grape products in ischemic heart disease." (PMID 34072098, 2021). "Engineered MSCs overexpressing Il-10 were transplanted in a diabetic mice model with myocardial infarction, which substantially suppressed inflammation, improved cardiac functional recovery, alleviated cardiac injury, decreased apoptosis of cardiac cells, and increased angiogenesis." (PMID 35097003, 2021). "Since IL-10 is increased at later time points following myocardial infarction and has potent anti-inflammatory effects, it would be anticipated that IL-10 might play an important role in the resolution of inflammation." (PMID 33041853, 2020). "IL-10, which is a powerful anti-inflammatory cytokine, reduces the extent of hypertrophy in response to pressure overload and angiotensin II, improves cardiac function and inhibits adverse remodeling post-myocardial infarction." (PMID 33192505, 2020). "Here, we determined whether heme toxicity and impaired heme clearance contribute to diabetic myocardial infarction injury and assessed IL-10 as a therapeutic agent for diabetic myocardial infarction." (PMID 32879134, 2020). "Likewise, treatment with IL-10 produces beneficial effects in animal models of myocardial infarction and pressure overload hypertrophy." (PMID 33192505, 2020). "However, it has been reported that FGF-9 enhanced M2 differentiation post-myocardial infarction accompanying with significantly elevated IL-10 secretion." (PMID 31852428, 2019). "Moreover, exercise training improved the inflammatory profile by increasing the levels of the anti-inflammatory cytokine IL-10 in post-myocardial infarction patients." (PMID 28526870, 2017). "In addition, patients with acute myocardial infarction showed higher TNF-α/IL-10 ratios when compared to the control group, demonstrating an important inflammatory imbalance." (PMID 25340545, 2014). "However, a correlation between the anti-inflammatory cytokine IL-10 and acute myocardial infarction in humans has been shown." (PMID 23929312, 2013). "Moreover, IL-10 promotes regenerative healing in injured skin, recovery from spinal cord injury, and myocardial infarct recovery, thus its production in response to E-selectin likely contributes to protection rather than pathogenesis." (PMID 21701687, 2011). "In our study, IL10 production was significantly decreased in comparison with normal subjects in both patients undergoing left ventricular remodeling and those not undergoing left ventricular remodeling, immediately after myocardial infarction." (PMID 20467464, 2010). "Interleukin-10 (IL-10) is a potent immunomodulatory cytokine widely explored as a therapeutic agent for diseases, including myocardial infarction (MI)." (PMID 39882328, 2024). "In a mouse model of myocardial infarction, MSCs injection significantly reduced the M1 phenotype of macrophages, decreased the expression of interleukin-1β (IL-1β) and IL-6, increased the expression of IL-10, and increased alternate monocyte/macrophage activation." (PMID 36768406, 2023). "In acute myocardial infarction (MI) models, IL-10 suppresses in vivo inflammatory responses, which contributes to improved myocardial recovery." (PMID 37138792, 2023). "In further studies, high IL-10/TNF-α ratios were associated with a better outcome in children with malaria infections, with a reduced infection susceptibility in severe burn injury patients or with improved outcome in experimentally induced myocardial infarction." (PMID 33582876, 2021). "In addition, IL-10 can also modify the macrophage phenotype into less inflammatory cell (M2), and has protective role in ventricular remodeling after experimentally induced myocardial infarction." (PMID 33495783, 2021).